PWWP4 (PWWP domain containing 4)
Gene: Protein-coding gene on chromosome X (153,266,152 to 153,279,145, forward strand). Ensembl gene ENSG00000278803.
Homologues: Orthologues: rat Pwwp4 (16% identical), mouse Pwwp4a (16% identical), mouse Pwwp4b (16% identical), mouse Pwwp4c (16% identical), mouse Pwwp4d (16% identical), tropical clawed frog pwwp3a (10% identical), zebrafish si:dkey-57k2.7 (6% identical). Paralogues in human: PWWP3B (14% identical), PWWP3A (12% identical).